Y_RNA (Y RNA )
Gene: Miscellaneous RNA gene on chromosome 3 (149,094,353 to 149,094,462, reverse strand). Ensembl gene ENSG00000201031.
Homologues: Orthologues: chimpanzee Y_RNA (98% identical), macaque Y_RNA (91% identical). Paralogues in human: RNY1 (87% identical), Y_RNA (86% identical), RNY1P11 (85% identical), Y_RNA (84% identical), Y_RNA (83% identical), RNY1P8 (82% identical), Y_RNA (82% identical), Y_RNA (81% identical), RNY1P10 (80% identical), Y_RNA (80% identical), Y_RNA (79% identical), RNY1P12 (78% identical), and 97 more.